INS (insulin)
Diseases named in the same sentence as INS in open-access papers (continued):
Sharing a sentence is not in itself a finding about the gene and the disease.
Insulin resistance (continued). "Regarding artichoke extract supplementation (ALE), two RCTs observed that ALE supplementation significantly decreased insulin concentration and improved insulin resistance in the TT genotype of the rs7903146 variant of TCF7L2." (PMID 36155628, 2022). "Of note, as described by others and us before, Cyp7b1 is tightly associated with insulin resistance and cold-exposed Cyp7b1−/− mice seem to be insulin-resistant." (PMID 35478959, 2022). "Hyperthyroidism is associated with decreased insulin sensitivity and insulin resistance, which impairs glucose homeostasis and leads to hyperglycemia." (PMID 35807200, 2022). "This supports findings from a recent study of 40 GDM women from Bangladesh with increased BMI (≥23 kg/m2) where GDM was associated with a combination of both insulin resistance and inadequate insulin secretion." (PMID 36295825, 2022). "Podocytes are insulin sensitive renal cells, and thus the insulin resistance is more likely to cause kidney damage." (PMID 35209907, 2022). "According to the etiology, DM can be either type 1 DM (T1DM) that is characterized by complete loss of insulin or T2DM that is associated with insulin resistance (IR) and peripheral insulin ineffectiveness." (PMID 35265366, 2022). "Obesity often causes insulin resistance, leading to hyperglycemia, which, in turn, affects the secretion of insulin by the pancreas to maintain glucose homeostasis." (PMID 36501200, 2022). "Two other studies found that small lambs at birth or those derived from restricted or overfeeding of dams during pregnancy had elevated insulin concentrations compared to their counterparts, in association with evidence of insulin resistance." (PMID 36230395, 2022). "The metabolic syndrome has its own set of underlying risk factors of which hyperinsulinemia and insulin resistance, defined as a subnormal response (of blood glucose levels) to insulin, are considered the most important." (PMID 35897752, 2022). "Pro-inflammatory cytokines, such as TNF-α and IL-6, disrupt the insulin signaling pathway, and cause insulin resistance." (PMID 35745208, 2022). "In particular, a positive association between adiponectin levels and insulin secretion was identified with an index incorporating an adjustment for insulin resistance." (PMID 35628332, 2022). "It is known that T2DM is associated with insulin resistance and increased serum insulin levels, which are required to control the glucose burden, and insulin resistance is responsible for the pathogenicity of T2DM and beta-cell failure." (PMID 36276816, 2022). "Insulin resistance is a state of insensitivity of cells to insulin and is commonly caused by defects in the insulin signaling pathway." (PMID 36499769, 2022). "C-P can indirectly reflect the concentration of insulin, and abnormally increased insulin content, together with insulin resistance, is an independent risk factor contributing to the development of CSVD." (PMID 35775047, 2022). "Insulin resistance reduces the ability of insulin to decrease production of these enzymes, leading to a loss of homeostasis of hepatic gluconeogenesis." (PMID 35968003, 2022). "Insulin has both pro‐atherogenic and anti‐atherogenic properties, which alter the risk of cardiovascular events depending on the presence of insulin resistance and hyperinsulinemia." (PMID 35467783, 2022). "Overt diabetes is associated with markedly reduced insulin-mediated suppression of lipolysis (adipose tissue insulin resistance), resulting in release of excess fatty acids that are converted to ketone bodies by the liver." (PMID 35405935, 2022). "The present study demonstrated that LDs in β cells accumulated more in patients with type 2 diabetes than in normal glucose-tolerant subjects and that LD accumulation was associated with insulin resistance, hyperglycemia and decreased insulin secretion." (PMID 36204103, 2022).
Insulin resistance (continued). "High-sucrose diet (HSD) is a time-efficient model widely used in rats for induction of whole body insulin resistance, associated with elevated serum glucose and insulin levels." (PMID 36297523, 2022). "Further, a deprivation in sleep can also cause impaired insulin sensitivity, and insulin resistance is a key factor in the pathogenesis of NAFLD." (PMID 35055407, 2022). "An altered gut microbiota has been associated with insulin resistance, a metabolic dysfunction consisting of cellular insulin signaling impairment." (PMID 35574036, 2022). "This demonstrates that reduced hepatic insulin clearance causes insulin resistance together with hepatic steatosis, independently of visceral obesity and lipolysis." (PMID 36009446, 2022). "T2DM is closely associated with insulin resistance (IR), a pathophysiological condition characterized by impaired insulin action on insulin-sensitive tissues, including skeletal muscle, liver and adipose tissue." (PMID 36703726, 2022). "Abnormal insulin secretion causes hyperglycemia, which will stimulate the development of hyperinsulinemia, reduce the number of insulin receptors, and aggravate insulin resistance." (PMID 36141135, 2022). "Insulin resistance (IR) is a state of decreased sensitivity and responsiveness to the action of insulin and has bee identified as a hallmark of T2DM, even preceding diabetes for several years." (PMID 35524263, 2022). "On the one hand, RGS2 is associated with adipogenesis, obesity, and metabolic syndrome, and is also associated with insulin resistance by blocking insulin signal translation in adipocytes through interaction with the Gαq protein." (PMID 36497154, 2022). "Myostatin concentrations are elevated in sarcopenic obesity, negatively associated with insulin sensitivity indices and positively with measures of insulin resistance." (PMID 35287731, 2022). "The main cause of children’s insulin resistance is the typical lipid distribution pattern, that is, increased deposition of lipids in insulin sensitive tissue such as the liver, skeletal muscle and viscera." (PMID 36419769, 2022). "Lactate is implicated in insulin resistance, resulting in reduced insulin-dependent glucose uptake in skeletal muscle and dysregulated insulin signaling." (PMID 36517845, 2022). "Insulin has an important role in T cell function, promoting anti-inflammatory T helper 2 cell response, whereas insulin resistance is associated with proinflammatory T helper 1 cell response." (PMID 36366375, 2022). "T2DM is characterized predominantly by insulin resistance with relative insulin deficiency, which increases the insulin demand of insulin-target tissues." (PMID 36438767, 2022). "Most of the T2D loci are associated mainly with insulin production and the β-cell function with a significantly smaller number of genetic variants which seemingly affect insulin resistance." (PMID 35627115, 2022). "In the current study LFC was also positively associated with insulin resistance markers such as fasting insulin, M-value, HOMA-IR and HbA1c, when adjusted for sex and age." (PMID 36261605, 2022). "As one of the causes of T2D, insulin resistance is a pathological condition in which cells fail to respond normally to insulin stimulation." (PMID 36230963, 2022). "Over-production of UA directly inhibits insulin signaling in hepatocytes, so UA is referred to as a risk factor for insulin resistance." (PMID 35928270, 2022). "One of the main factors that contribute to the development of DM2 is insulin resistance, which causes an increase in serum insulin concentration." (PMID 35019122, 2022). "The immediate onset of systemic insulin resistance in response to HFD-feeding is linked to impaired hepatic insulin action, which is followed by peripheral insulin resistance in adipose and muscle tissue." (PMID 36158197, 2022). "Type 2 DM is caused by both peripheral insulin resistance and relative deficiency of β cell insulin secretion." (PMID 35052857, 2022).
Insulin resistance (continued). "Even though oral antihyperglycemic agents can lower plasma glucose levels by improving insulin secretion or reducing insulin resistance, they are associated with many other adverse effects." (PMID 35807526, 2022). "A large-scale meta-analysis of GWAS has been carried out using several cohorts with insulin sensitivity, processing, and secretion measurements to detect novel genetic variants related to insulin resistance." (PMID 35627115, 2022). "In a pathological study of Hisayama inhabitants, increased levels of two-hour post-load sugar, fasting insulin, and homeostasis model assessment of insulin resistance were remarkably related to enhanced risk of neuritic plaques." (PMID 36258952, 2022). "An association among COBLL1 rs7607980 C allele, lower serum insulin levels, and lower insulin resistance was reported in overweight and obese children." (PMID 35626321, 2022). "M1 macrophage deletion increases sensitivity to insulin in obese mice, and a reduction in M2 macrophages predisposes lean mice to insulin resistance." (PMID 35053615, 2022). "Insulin resistance in old age is associated with impaired compensation mechanisms related to decreased insulin secretion by the pancreas." (PMID 35054072, 2022). "Abnormal Changes in signaling proteins associated with insulin signaling clearly play a crucial part in the insulin resistance state." (PMID 36160451, 2022). "Since insulin resistance and hyperinsulinemia are common in obese individuals and associated with increased risk of asthma, we used diet-induced obese mice to study how insulin induces airway hyperreactivity." (PMID 36107629, 2022). "Insulin signaling is connected to Type 2 diabetes and related diseases like obesity, hyperlipidemia, and atherosclerosis that are caused by insulin resistance." (PMID 35502176, 2022). "In endothelial cells, miR-155 was repressed by insulin and insulin resistance due to impaired signaling by a variant of IRS1 (Arg972 IRS1) resulting in an upregulation of miR-155." (PMID 35955975, 2022). "Insulin resistance is linked to attenuating insulin activity and increasing insulin secretion to normalize serum glucose concentrations." (PMID 35057420, 2022). "Our finding of higher insulin levels likely reflects an underlying increase in insulin resistance, as both acute circadian misalignment and chronic nightshift work induce insulin resistance." (PMID 35615722, 2022). "Previous studies used a zebrafish model to study how hyperinsulinemia-induced insulin resistance associated with immune response exhibited the inhibition of key mediators of the insulin-signaling pathway." (PMID 35955446, 2022). "One of the best documented effects of obesity is to cause hepatic insulin resistance that triggers a compensatory increase in insulin secretion to maintain normoglycemia." (PMID 35984550, 2022). "At the molecular level, insulin resistance in skeletal muscle is associated with reduced insulin signaling to glucose transport and glycogen synthesis, accumulation of lipid metabolites and abnormalities in mitochondrial oxidative metabolism." (PMID 36387850, 2022). "It has a 500 times higher affinity to insulin than other IGFBPs and it is proven to be associated with insulin resistance (IR), development of metabolic syndrome (MetS), and consequently cardiovascular diseases." (PMID 35625639, 2022). "Cognitive deficits are associated with insulin resistance, and impairment of insulin-dependent glucose uptake mechanisms can lead to impaired energy metabolism." (PMID 35563135, 2022). "Impaired insulin signaling in T2DM causes neuronal insulin resistance in patients, which promotes α-syn accumulation." (PMID 35255986, 2022). "T2D is the combination of an insulin production deficiency and an insulin resistance primarily in muscle, liver and adipose tissues, the main targets of insulin." (PMID 36247456, 2022).
Insulin resistance (continued). "The most important factors leading to such increasing risks are (i) deficiency of insulin secretion developing with age and (ii) growing insulin resistance caused by a change in body composition and sarcopaenia." (PMID 36962350, 2022). "Chronically elevated lipid and lipoprotein profiles are associated with glucose intolerance, insulin resistance, and the onset of type 2 diabetes by inhibiting insulin-mediated glucose transporters in skeletal muscle." (PMID 35406092, 2022). "Smoking causes changes in insulin secretion by pancreatic cells and can also cause insulin resistance associated with impaired glucose metabolism." (PMID 36443727, 2022). "Insulin action is inevitably linked to proper mitochondrial function, and, not surprisingly, aberrant mitochondria in the brain are connected to insulin resistance, metabolic syndrome, diabetic encephalopathies, neurodegenerative diseases, and aging." (PMID 35052794, 2022). "Current results show that irisin levels are lower in PWS than in controls independent of BMI, and that a strong association links irisin to measures of insulin resistance, particularly insulin OGTT120 levels." (PMID 35774143, 2022). "Type I diabetes is caused by insulin secretion deficit, while type II diabetes is accompanied with progressive rate of insulin resistance in liver and peripheral tissues, reducing β-cell mass, and deficient insulin secretion." (PMID 35082904, 2022). "T1DM is an autoimmune-mediated disease that is mainly insulin deficient, while insulin resistance is more prominent in T2DM." (PMID 36552599, 2022). "BCAA added to a high-fat diet caused a disruption in insulin signaling and induced insulin resistance in rats." (PMID 36361016, 2022). "There is extensive evidence linking dysfunction or loss of β-cells with reduced secretion of insulin and development of insulin resistance which is linked to IAPP amyloid formation." (PMID 35475576, 2022). "Almost 70% of type 2 DM (T2DM) is characterized by insulin secretion deficiency and insulin resistance with concurrent diabetic dyslipidaemia." (PMID 35547000, 2022). "Type 2 diabetes (T2D) is triggered by insulin resistance (IR), which leads to an increased demand of peripheral tissues for insulin and, as a consequence, causes the functional failure of β-cells." (PMID 35008906, 2022). "The release of catecholamines and a rise in serum glucocorticoid concentrations caused by psychological stress enhance the requirement for insulin and insulin resistance." (PMID 36258973, 2022). "Aging is a major risk factor for type 2 diabetes, in which peripheral insulin resistance and the inadequate secretion of insulin result in chronic hyperglycemia and various complications." (PMID 35563231, 2022). "Insulin resistance (IR) is associated with a reduction in the amplitude of insulin cycling and an increase in the basal level of insulin, creating more of a constant rather than oscillatory pattern of insulin stimulation of its receptor." (PMID 35163806, 2022). "T2DM is caused by a combination of decreased tissue insulin sensitivity, insulin resistance (IR), and pancreatic-cell failure." (PMID 35883721, 2022). "In healthy individuals, low serum phosphate levels are associated with reduced insulin resistance (IR); phosphate supplementation, especially when co-ingested with glucose, can, in turn, improve insulin sensitivity." (PMID 35966090, 2022). "The negative regulatory role of protein tyrosine phosphatase 1B (PTP-1B) in insulin signaling prevents insulin receptors from binding to insulin, which in turn causes insulin resistance and ultimately leads to T2DM." (PMID 35721172, 2022). "The prevailing thought is that the increase in plasma insulin in people with obesity is a compensatory response to obesity-associated insulin resistance." (PMID 35054781, 2022).
Insulin resistance (continued). "Regarding Akkermansia, this genus has been positively associated with overall health, increased insulin sensitivity, and glucose tolerance, and weight loss, and has been negatively associated with insulin resistance, dyslipidemia and BMI." (PMID 35277033, 2022). "The elevated levels of endogenous insulin, an anabolic hormone, are associated with insulin resistance and result in weight gain, which in turn exacerbates insulin resistance." (PMID 35734406, 2022). "On the other hand, excess free fatty acids (high lipolytic rate) are linked with low insulin sensitivity (or insulin resistance)." (PMID 36530555, 2022). "High levels of androgen also reduce insulin sensitivity, which is why insulin resistance (IR) is usually linked to PCOS." (PMID 36662487, 2022). "The underlying mechanism of GDM is due to the reduction of insulin secretion or the development of insulin resistance (IR)." (PMID 36076264, 2022). "A 32-year follow-up investigation confirmed that impaired insulin secretion, glucose intolerance and insulin resistance were all associated with a higher risk of AD." (PMID 35745036, 2022). "Insulin resistance is due to either a loss in tissue responsiveness when the maximal response to insulin is reduced or a loss in insulin sensitivity when more insulin is needed to elicit similar responses." (PMID 36153497, 2022). "This will result in such consequences as insulin resistance, and decreased insulin gene expression causing reduced insulin secretion by beta-pancreatic cells." (PMID 35794663, 2022). "It is suggested that elevated FFAs and the accumulation of lipid in tissues like muscle and liver leads to disruption in insulin signalling, causing insulin resistance and impaired endothelial function." (PMID 35676248, 2022). "Other study also revealed that the G allele at rs35767 was associated with reduced fasting insulin levels and insulin resistance." (PMID 35094288, 2022). "Insulin deficiency in T1D as well as insulin resistance and insufficient insulin secretion from impaired pancreatic β cells in T2D result in increased glucose production in the liver, which is the major cause of hyperglycemia in diabetic patients." (PMID 35074429, 2022). "These include polymorphisms in genes affecting carbohydrate metabolism, insulin secretion, insulin resistance, and inflammation." (PMID 36009479, 2022). "An association between the COBLL1 rs7607980 C allele, lower serum insulin levels, and lower insulin resistance in overweight and obese children has also been indicated." (PMID 36009479, 2022). "Many studies showed that visceral fat accumulation and decreased plasma adiponectin concentration were associated with insulin sensitivity, insulin resistance, and vascular inflammation." (PMID 35812109, 2022). "Insulin resistance leads to insulin imbalance and predisposes women with a GDM-complicated pregnancy and their offspring to develop type 2 diabetes mellitus (T2DM) and cardiovascular diseases (CVD) later in life." (PMID 36080270, 2022). "Insulin resistance (IR) is a reduction in glucose utilization by target organs in response to insulin and is an important risk factor for cardiovascular disease." (PMID 35509833, 2022). "There are also genetic causes of insulin resistance, including genetic diseases (myotonic dystrophy, Rabson–Mendenhall syndrome, Werner syndrome) and abnormalities in the function of insulin antibodies and insulin receptors." (PMID 35406013, 2022). "Our study aimed to investigate the association between the novel non–insulin‐based metabolic score for insulin resistance (METS-IR) index and pre-hypertension (HTN) or HTN in normoglycemia Japanese participants." (PMID 35370984, 2022). "In the vascular system, insulin stimulation persuades vasodilation through NO production, and during insulin resistance, there is impairment of NO synthesis, which causes altered vascular function." (PMID 35455055, 2022).